SLC22A16 (solute carrier family 22 member 16)
Description:
Facilitative organic cation transporter that mediates the transport of carnitine as well as the polyamine spermidine. Mediates the partially Na(+)- dependent bidirectional transport of carnitine. May mediate L-carnitine secretion from testis epididymal epithelium into the lumen which is involved in the maturation of spermatozoa.
Synonyms: CT2; FLIPT2; OCT6; OKB1; OAT6; HEL-S-18; dJ261K5.1
Tractability: Small molecule: it belongs to a druggable protein family. Antibody: UniProt places it where antibodies can reach, with high confidence; its Gene Ontology location is reachable by antibodies, with high confidence; UniProt predicts a signal peptide or a membrane-spanning region; the Human Protein Atlas places it where antibodies can reach.
Target class: SLC superfamily of solute carriers; Electrochemical transporter; SLC22 family of organic cation and anion transporters; Transporter
Safety:
Unwanted effects reported when the protein is acted on. In parentheses: how it was acted on, where the effect was seen, and who reports it.
dose delay (source: ClinPGx)
Drug Toxicity (source: ClinPGx)
nausea (source: ClinPGx)
neutropenia (source: ClinPGx)
neutropenia and a dose delay (source: ClinPGx)
Gene: Protein-coding gene on chromosome 6 (110,424,687 to 110,476,681, reverse strand). Ensembl gene ENSG00000004809.
Subcellular location: Cell membrane
Subcellular location (Human Protein Atlas): Cytosol; Plasma membrane
Pathways (Reactome):
Transport of small molecules: SLC-mediated transport of organic cations
Gene Ontology:
Molecular function: amine transmembrane transporter activity; carnitine transmembrane transporter activity; spermidine transmembrane transporter activity; transmembrane transporter activity
Biological process: acid secretion; carnitine transmembrane transport; carnitine transport; flagellated sperm motility; single fertilization; spermidine transmembrane transport; transmembrane transport; amine transport
Cellular component: membrane; plasma membrane
Genetic constraint (gnomAD): Loss-of-function variants: 49 observed, 48.87 expected, observed/expected ratio (o/e) 1, 90% interval 0.8 to 1.27. The upper end of that interval is the gene's LOEUF score, 1.27, which puts it in group 5 of 6, group 1 being the genes least tolerant of losing a copy. Missense variants: 705 observed, 707.68 expected, observed/expected ratio (o/e) 1, 90% interval 0.94 to 1.06. Synonymous variants: 288 observed, 276.34 expected, observed/expected ratio (o/e) 1.04, 90% interval 0.95 to 1.15.
Homologues: Orthologues: chimpanzee SLC22A16 (99% identical), macaque SLC22A16 (96% identical), pig SLC22A16 (65% identical), dog SLC22A16 (63% identical), rabbit SLC22A16 (57% identical), tropical clawed frog slc22a16 (56% identical), rat Slc22a16 (55% identical), mouse Slc22a16 (53% identical), zebrafish slc22a16 (48% identical), Drosophila melanogaster Orct2 (30% identical), Drosophila melanogaster Orct (28% identical), Caenorhabditis elegans oct-1 (27% identical), and 37 more. Paralogues in human: SLC22A4 (31% identical), SLC22A5 (31% identical), SLC22A13 (28% identical), SLC22A1 (27% identical), SLC22A12 (27% identical), SLC22A2 (26% identical), SLC22A15 (26% identical), SLC22A7 (25% identical), SLC22A3 (25% identical), SLC22A6 (24% identical), SLC22A24 (24% identical), SLC22A8 (24% identical), and 10 more.
Diseases named in the same sentence as SLC22A16 in open-access papers:
SLC22A16 is named in the same sentence as 17 diseases in open-access papers, as found by Europe PMC text mining. Sharing a sentence is not in itself a finding about the gene and the disease. The quoted sentences say what the papers report.
breast carcinoma (8 papers, 2010 to 2025). "Variant alleles of SLC22A16 are associated with response and levels of toxicity caused by doxorubicin and cyclophosphamide therapy in the treatment of breast cancer which is consistent with the fact that doxorubicin is a substrate this transporter." (PMID 29559890, 2018). "In this study, we explored the role of ABCB1 (rs10276036 C/T) and SLC22A16 (rs12210538 A/G) gene polymorphisms in the development of grade 3/4 febrile neutropenia in Iranian breast cancer patients who were administered DOX-based chemotherapy." (PMID 28036387, 2016). "In this study, we explored the effect of 2 common polymorphisms in ABCB1 (rs10276036 C/T) and SLC22A16 (rs12210538 A/G) on the development of grade 3/4 febrile neutropenia in Iranian breast cancer patients." (PMID 28036387, 2016). "In breast cancer cohorts, variant alleles of SLC22A16 (rs714368) were found to be related to higher exposure levels of doxorubicin and doxorubicinol and dose delays by anthracycline toxicities (lower with rs714368, rs6907567, rs723685 and higher with rs12210538)." (PMID 35456712, 2022). "Furthermore, earlier studies confirmed the association of SNPs within SLC22A16 with toxic side effects in chemotherapy in breast cancer patients." (PMID 32235849, 2020). "Furthermore, Bray and colleagues studied the association of polymorphic variants of the ABCB1 and SLC22A16 genes with drug toxicity in breast cancer patients treated with DOX, and found that polymorphisms are associated with the development of toxicities." (PMID 28036387, 2016). "Variant alleles in the ABCB1, SLC22A16 and CYP2B6 genes are associated with response to AC therapy in the treatment of breast cancer." (PMID 20179710, 2010). "The results suggest that the risk of death, disease progression or recurrence of breast cancer is modified by genetic variants of nuclear receptors (NR1/2, PGR), genes engaged in main metabolic pathway of doxorubicin (SLC22A16) and doxorubicin-progesterone-related gene (AKR1C3)." (PMID 32235849, 2020). "The ‘double hit’ as such, similarly as for the SLC22A16 in OS analysis, point out the relations between physiological, metabolic and signaling pathways of progesterone and the metastatic ability of breast cancer cells, as well as the revival of dormant micrometastases." (PMID 32235849, 2020). "Expression of ABCB1, ABCC2, ABCG2, SLC22A16, and SLCO1A2 was significantly higher in normal breast tissue compared to tumorous tissue, while SLC22A1 and the tumor marker ESR1 showed a significantly higher expression in breast cancer tissue." (PMID 35008681, 2021). "Germ line DNA samples from 230 patients with breast cancer on AC therapy were genotyped for the following SNPs: ABCB1 C1236T, G2677T/A and C3435T, SLC22A16 A146G, T312C, T755C and T1226C, CYP2B6*2, *8, *9, *3, *4 and *5, CYP2C9*2 and *3, CYP3A5*3 and CYP2C19*2." (PMID 20179710, 2010). "SLC22A2, SLC22A16, and SLCO1A2 were not expressed in any of the investigated breast cancer cell lines (Ct values > 35)." (PMID 35008681, 2021).
leukopenia (3 papers, 2016 to 2025). "Among patients carrying the GG+GA genotype of the SLC22A16 gene, leukopenia grade significantly increased after the fourth cycle, and neutropenia grade increased after the second cycle compared to baseline p-value < 0.05)." (PMID 40283974, 2025). "In this study polymorphic variants in genes encoding membrane transporters, both influx (SLC22A16) and efflux ones (ABCB1, ABCG2, ABCC2), were the independent predictors of all studied symptoms of FAC myelotoxicity, excluding overall leukopenia." (PMID 29507678, 2018). "Qualitative hematological toxicity variables, including thrombocytopenia, leukopenia, neutropenia, lymphocytopenia, and anemia, were assessed at five different time points for their correlation with various alleles of the CYP2C19, ALDH3A1, SLC22A16, and ABCB1 genes." (PMID 40283974, 2025).
neutropenia (3 papers, 2016 to 2025). A decrease in the number of neutrophils found in the blood. "Regarding the SLC22A16 gene, the neutropenia grade increased significantly following the second and fourth cycles, while the lymphocytopenia grade increased significantly after the fourth cycle among patients with the AA genotype (p < 0.05)." (PMID 40283974, 2025). "Apart from the ABC family, another transporter gene established as independent predictive factor for hematological toxicities - recurrent neutropenia, was SLC22A16." (PMID 29507678, 2018).
melanoma (2 papers, 2018 to 2019). A malignant, usually aggressive tumor composed of atypical, neoplastic melanocytes. "We demonstrate similar findings in vitro wherein knockdown of SLC22A16 in melanoma cells led to increased expression of SLC22A1 and SLC22A3." (PMID 30518936, 2018). "In addition, the abundant expression of the solute carrier family 22 member 16 (SLC22A16) gene, a carnitine transporter, has been reported in ovarian carcinoma cell lines, and its upregulation helped induce melanoma cell death when combined with chemotherapy." (PMID 31892232, 2019).
colon carcinoma (1 paper, 2014). "As for spermidine uptake by the carnitine transporter SLC22A16, the uptake activity in human colon carcinoma HCT116 cells (Vmax = 23.1 pmol/107 cells/h) seems to be lower compared to the spermidine uptake activity by hOCT2, although the Km value is very low (0.35 μM)." (PMID 25019617, 2014).
gastric cancer (1 paper, 2020). A primary or metastatic malignant neoplasm involving the stomach. "In gastric cancer patients, SLC22A16 upregulation independently predicted poor OS and RFS, in early gastric cancer and poor OS in advanced gastric cancer." (PMID 32235849, 2020).
leukemia (1 paper, 2025). A malignant (clonal) hematologic disorder, involving hematopoietic stem cells and characterized by the presence of primitive or atypical myeloid or lymphoid cells in the bone marrow and the blood. "Thus, we conclude that PSMB10 decreases the intracellular drug concentration in leukemia cells by inhibiting SLC22A16-mediated drug endocytosis." (PMID 40462177, 2025). "The increased PSMB10 promotes the stemness maintenance of chemotherapeutic drug-resistant leukemia cells via the inhibition of SLC22A16-mediated drug endocytosis and RPL6/RPS6-MDM2-P21 pathway-initiated senescence, as well as the MHC-I protein degradation-induced escape of CTL killing." (PMID 40462177, 2025).
Obesity (1 paper, 2022). Accumulation of substantial excess body fat. "As such, some of the genome-wide associations reported here (e.g., carnitine and SLC22A16) may be translationally relevant beyond transfusion medicine when interpreted in the context of markers relevant to specific diseases (e.g., carnitine metabolism and obesity)." (PMID 36395887, 2022).
schizophrenia (1 paper, 2018). A major psychotic disorder characterized by abnormalities in the perception or expression of reality. "Interestingly, SLC22A16 is located within a schizophrenia susceptibility locus in chromosome 6q." (PMID 29559890, 2018).
cancer (9 papers, 2010 to 2025). A tumor composed of atypical neoplastic, often pleomorphic cells that invade other tissues. "A previous study reported that the SLC22A16 gene was associated with the doxorubicin dose in female cancer patients." (PMID 31088516, 2019). "Expression of the SLC22A16 gene in cancer cells was associated with increased sensitivity to the cytotoxic effects of DOX." (PMID 28036387, 2016). "SLC22A16 expression in cancer cells is associated with an increased sensitivity to the cytotoxic effects of doxorubicin." (PMID 20179710, 2010). "Efflux transporters (e.g., P-gp/ABCB1, ABCC1, and ABCG2) and influx transporters (e.g., SLC22A16) are involved in Dox resistance in cancer cells." (PMID 31293428, 2019). "We observed an upregulation of the organic cation transporter SLC22A16 following exposure with cold plasma-derived oxidants in a subset of cancer cell lines, which was inhibited by antioxidant catalase and Ca2+ channel inhibitor BTP2." (PMID 30518936, 2018).
tumor (7 papers, 2015 to 2025). "Regarding the SLC22A16 gene, patients carrying the GG+GA genotype exhibited a significant increase in fatigue and skin toxicity severity after cycle one compared to before chemotherapy (p < 0.05)." (PMID 40283974, 2025). "Recently, we demonstrated that plasma treatment increased the expression of SLC22A16 in tumor cells, which led to an intracellular accumulation of anthracyclines resulting in synergistic tumor toxicity." (PMID 31931281, 2020). "The shortened OS was connected with the presence of NR1/2 rs3732359 AA, SLC22A16 rs7756222 CC, as well as SLC22A16 rs9487402 allele G and clinical factors belonging to TNM classification: tumor size >1 cm, nodal involvement and presence of metastases." (PMID 32235849, 2020). "Endoribonuclease-prepared siRNAs (esiRNA)-mediated knockdown of SLC22A16 inhibited the additive cytotoxic effect in tumor cells." (PMID 30518936, 2018). "The observed synergistic effects in tumor cells was due to enhanced intracellular doxorubicin accumulation via upregulation of the organic cationic transporter SLC22A16 by plasma treatment." (PMID 30518936, 2018). "SLC22A16 gene expression following exposure to plasma was also investigated in other tumor cell lines PC-3, MDA-MD231, MCF10A, and SW480 with the first two showing an upregulation while the latter two did not." (PMID 30518936, 2018).
SLC22A16 also shares sentences with these, for which no sentence is quoted: anemia (1 paper); carnitine deficiency (1); mucositis (1); ovarian carcinoma (1); Thrombocytopenia (1); triple-negative breast carcinoma (1).